TNF (tumor necrosis factor)
Diseases named in the same sentence as TNF in open-access papers (continued):
Sharing a sentence is not in itself a finding about the gene and the disease.
Obesity (continued). "NAFLD, insulin resistance, and obesity increase adipocyte lipolysis and have a stimulatory effect on immune cells such as macrophages and lymphocytes, leading to a chronic state of low-grade inflammation with increased production of proinflammatory cytokines, including TNF-α and IL-6." (PMID 33807573, 2021). "Obesity induces a state of chronic, low-grade inflammation in the adipose tissue that is accompanied by the local secretion of several pro-inflammatory cytokines and chemokines, especially TNFα, attenuating insulin action and resulting in insulin resistance through activation of the JNK pathway." (PMID 34685582, 2021). "Severity of obesity resulted to be associated with lower plasma levels of oxytocin (p = 0.053), vitamin D deficiency (p = 0.006) and higher plasma levels of IFN-γ (p = 0.004), IL-6 (p = 0.013), IL-7 (p = 0.013), TNF-alpha (p = 0.036) and chemokine ligand 3 (CCL3) (p = 0.013, R2 = 0.03)." (PMID 33809270, 2021). "Importantly, agents targeting tumor necrosis factor-α signaling were effective for EP treatment, suggesting that the pathophysiology of EP and obesity shared some cytokines that are known to contribute to features of the MetS, such as hypertension, dyslipidemia, and insulin resistance." (PMID 34970217, 2021). "These improvements in insulin markers in the population with obesity are important because are against of obesity pathophysiology, that is characterized by a state of low-grade systemic inflammation due to increased secretion of inflammatory cytokines, such as TNF-α and IL-6." (PMID 34568974, 2021). "Existing studies have shown that obesity may be associated with a detrimental response to anti-TNF treatments in PsA and RA patients in comparison to non-obese or normal weight patients." (PMID 34300360, 2021). "From a mechanistic perspective, obesity can drive oncogenesis through the decreased secretion of adiponectin and the chronic production of adipokines, insulin, insulin-like growth factor, inflammatory cytokines and tumour necrosis factor including IL-6 and TNFa." (PMID 34014795, 2021). "Also, Leptin and TNF-α are involved in the pathogenesis of obesity and insulin resistance." (PMID 34039404, 2021). "The first evidence for adipose inflammation at the interface between obesity and metabolic dysregulation was provided by studies demonstrating increased production and secretion of the inflammatory cytokine tumor necrosis factor alpha (TNFα) from adipose tissues in obese rodents and human subjects." (PMID 33717092, 2021). "Besides, TNF-α may influence the fat metabolism and is positively correlated with circulating triglycerides (TG), obesity, and insulin resistance." (PMID 33997011, 2021). "In conclusion, our work showed effectiveness in treating obesity-associated diabetes as well as protective effect against CVD as shown by the AIP, which might be partly due to the attenuation of inflammatory mediators, TNF-α and IL-6." (PMID 33737713, 2021). "In this way, obesity and mitochondrial dysfunction dysregulate the production of WAT-derived circulating adipokines such as interleukins (IL)-6, IL-1β, and tumor necrosis factor (TNF)-α, which may exacerbate the state of low-grade, chronic inflammation observed in obesity." (PMID 34835983, 2021). "The direct molecular factors linking obesity and cancer are not fully understood, but the organ-dependent crosstalk between the adipose tissue and carcinomas via the vascular endothelial growth factor (VEGF), interleukin 6 (IL-6), tumor necrosis factor α (TNFα), and other mechanisms are implicated." (PMID 34638514, 2021). "Similarly to TNF-α, IL-6 levels increase with obesity and body fat." (PMID 34356649, 2021). "Inflammatory cytokines such as TNF-α are increased in chronic conditions such as type 2 diabetes mellitus and play a role in insulin resistance and has been suggested as an intermediary link between obesity and inflammatory diseases, including type 2 diabetes mellitus and heart disease." (PMID 33676486, 2021).
Obesity (continued). "In general, obesity is characterized by chronic inflammation and increased expression and release of proinflammatory neurohumoral factors, including adipokines such as leptin and adiponectin, and proinflammatory cytokines such as tumor necrosis factor-α (TNF-α), interleukin (IL)-1 and IL-6." (PMID 34088886, 2021). "Therefore, this evidence may support the regulative role of TNF-α on IL-6 and IL-10 concentration levels in adults with overweight or obesity who experimented an alteration of monocyte metabolism after exercise training." (PMID 34948868, 2021). "The characteristic profile of soluble factors in obesity and aging, such as decreased adiponectin, elevated levels of C-reactive protein (CRP), leptin, tumor necrosis factor-α (TNF-α), and interleukin 6 (IL-6), could lead to progressive loss of muscle mass and an increase in fat mass." (PMID 34676021, 2021). "In obesity, adipokines are dysregulated, whereby inflammatory cytokines such as TNF-α, IL-6, IFN-γ, and IL-1β are upregulated, resulting in a state of chronic low-grade inflammation called metabolic inflammation which underlies pathophysiology of obesity and metabolic syndrome." (PMID 32403230, 2020). "The genera Clostridium XI, Clostridium IV and Escherichia/Shigella, the biomarkers of the HFD group based on the LEfSe analysis, were found to be positively correlated with the proinflammatory cytokine TNF-α, indicating that these genera may have a proinflammatory role during obesity development." (PMID 32244807, 2020). "However, in pathological conditions such as obesity, dysfunctional adipocytes mostly produce and release pro-inflammatory adipokines such as leptin, tumour necrosis factor-α (TNFα), interleukin 6 (IL-6), interleukin 18 (IL-18), or resistin, which have atherogenic effects." (PMID 33081064, 2020). "Hence, NRG-4 and adiponectin expression change in a similar manner, while NRG-4 overexpression counteracts the expression of proinflammatory cytokines involved in obesity-induced adipose tissue inflammation, such as tumor necrosis factor α (TNFα) and interleukin 1β (IL1β)." (PMID 32655416, 2020). "An excessive production of estrogen and inflammatory cytokines such as interleukin (IL)-1, IL-6, and tumor-necrosis factor (TNF) due to elevated fat mass in individuals with obesity may contribute to dysregulated biological processes that support carcinogenesis." (PMID 33287442, 2020). "In the Lehmann-Kalata study, the authors found a statistically significant difference in TNF-a R1 (TNF-a receptor 1) salivary concentration between obese patients and people without obesity (higher in obese subjects), which could indicate an increase in TNF-a concentrations in people with obesity." (PMID 32598403, 2020). "Finally, we can state that IL-6 and TNF-α are the main players of inflammation in obesity." (PMID 32650509, 2020). "During obesity, adipocytes undergo hypertrophy that leads to an increase of adipose tissue size followed by hypoxia conditions, which contribute to the secretion of proinflammatory adipokines, such as TNFα, TGFβ, IL-6, and MCP-1 by adipocytes and other cells present in adipose tissue." (PMID 33133214, 2020). "Interestingly, some genes associated with obesity were also associated with AD by different genetic approaches: candidate gene approach FTO, by differentially expressed genes NRXN3, NPC1, NEGR1, or by GWAS approach: LEPR, BDNF, TNFα, and MTCH2." (PMID 32982666, 2020). "In addition, TNF-α has been shown to induce ROS production through activation of the nuclear factor B κ kinase subunit β (NF-κB) pathway, providing one of the possible links between inflammation and oxidative stress in obesity." (PMID 32971975, 2020). "Obesity is well-known to increase various pro-inflammatory adipokine concentrations in serum and plasma as well as adipose tissue, whereas mRNA expression levels showed that adipocytes co-cultivated with breast cancer cells also had significantly higher IL-6, IL-1β, and TNF-α levels." (PMID 32257945, 2020).
Obesity (continued). "Furthermore, stimulation of AMPK phosphorylation prevented HFD-induced insulin resistance and inflammation in adipose tissue through anti-inflammatory effects in obesity and attenuated lipopolysaccharide-induced secretion of proinflammatory cytokines such as TNF-α and MCP-1." (PMID 33204402, 2020). "Indeed, upon activation, JNK is translocated from the cytoplasm into the nucleus, thus promoting the expression of several pro-inflammatory genes and protein synthesis (e.g., IL-1β, TNFα, IL-8, and IL-6), impairing glucose tolerance by obesity-induced insulin resistance." (PMID 33322742, 2020). "Permeability of the BBB has previously reported to be increased in a mouse model of obesity-induced by high-fat diet, in which cognitive deficits were aggravated by excessive exposure of the brain to inflammatory cytokines, including LPS, IL-1β, IL-6, and TNFα." (PMID 32127019, 2020). "To identify signals in fat tissue that might induce YAP/TAZ activation during obesity, we analyzed whether palmitic acid or several cytokines, including TNFα, interleukin (IL)-1β, CCL2, and IL-6 are able to induce YAP/TAZ target gene expression in 3T3-L1 adipocytes." (PMID 33116140, 2020). "Elevated inflammatory cytokines IL-6 and TNF-α are majorly produced by increased M1 macrophages in obese AT and their altered circulating levels have been reported in patients with overweight and obesity, contributing to a local as well as systemic chronic inflammation." (PMID 32806722, 2020). "The reaction to obesity-related inflammation is the activation of the NF-ĸB transcription factor, which enhances, among others, the production of pro-inflammatory interleukins such as IL-1, IL-6 and TNF-α, and the concentration of C-reactive protein also increases." (PMID 32872598, 2020). "Additionally, TNF-α is positively correlated with BMI and this correlation could be considered an important factor in obesity pathogenesis." (PMID 32893859, 2020). "Obesity has been suggested to promote oxidative stress, as obesity promotes the infiltration and activation of macrophages and monocytes into adipose tissue which in turn release elevated levels of pro-inflammatory adipokines, such as tumor necrosis factor alpha (TNF-a) and interleukin-6 (IL-6)." (PMID 32231008, 2020). "The water extract of A. camphorata ameliorates high-fat diet-induced obesity in mice by maintaining intestinal integrity, regulating intestinal microbiota to reduce fat accumulation and serum TG level and reversing inflammatory factors such as IL-1β, IL-6 and TNF-α." (PMID 32932919, 2020). "Moreover, plasma levels of mature IL-18, activated by the NLRP3 inflammasome, and TNF, a cytokine that could be activated down-stream to NLRP3 activation, were increased with obesity and markedly reduced in inflammasome deficient mice." (PMID 31379826, 2019). "Moreover, obesity could induce an increase of the serum concentrations of IL-6, TNF-α, and IL-1β in obese rats." (PMID 30854010, 2019). "Overweight and obesity are clearly associated with alterations in the lipid profile and raise in the markers of systemic inflammation, including C-reactive protein (CRP) and proinflammatory cytokines, such as interleukin- (IL-) 1 beta (IL-1β), IL-6, and tumor necrosis factor alpha (TNF-α)." (PMID 31482005, 2019). "Obesity is associated with increased expression of adipokines including TNF-α, IL-6, and CCL2 which can cause damage to adipocytes and the release of FFAs, and the combined effect of TNF-α and FFAs may trigger further IL-8 production." (PMID 31443599, 2019). "Obesity is associated with a low-grade chronic systemic inflammatory state characterized by elevation of acute-phase proteins such as C-reactive protein (CRP) produced by the liver and IL-6, secreted by adipocytes and adipose tissue macrophages, as well as by an increase in TNF-α by adipose tissue." (PMID 31885787, 2019).
Obesity (continued). "However, obesity did not seem to be associated with the presence of perianal lesions, or response to treatment with immunomodulators or anti-TNFα agents." (PMID 31234447, 2019). "Interestingly, we observed increased levels of TNF-α and oxidative stress also in brain cortex of the HFD mice, confirming that neuroinflammation observed in the diet-induced obesity animal model may be linked to increase in TNF-α secretion." (PMID 31798417, 2019). "Hypertrophic or apoptotic adipocytes in individuals with obesity increased the pro-inflammatory status, due to the secretion of several molecules such as leptin, resistin, interleukin 6 (IL-6) and tumor necrosis factor-α (TNF-α) that can activate M1 macro-phage-response." (PMID 31118060, 2019). "However, in a state of accelerated progression induced by obesity, a detriment of pro-inflammatory IL-6 and TNF-α production within the bone marrow may support the disruption of both myelopoiesis and lymphopoiesis." (PMID 31616626, 2019). "Hence, obesity-associated increases in CCL2 and CCL5 levels, together with an increase in estrogen and pro-inflammatory mediators such as leptin, IL-6, IL-1β, and TNF-α could facilitate MDSC accumulation." (PMID 31475003, 2019). "Furthermore, although specific studies are lacking in relation to upper airway musculature, increases in TNF-α in the context of other conditions (e.g., obesity) may promote muscle dysfunction and therefore enhance the likelihood of upper airway dysfunction." (PMID 30678164, 2019). "Similarly, TNF-α mRNA expression was directly correlated with the BMI (r = 0.34; P = 0.02, n = 48), and TNF-α mRNA and protein levels were significantly higher (P = 0.005 and P = 0.007, respectively) in individuals with obesity as compared to those with normoweight or overweight controls." (PMID 31443599, 2019). "However, the high TNFα exposure that is provided by obesity may induce TNFα resistance that facilitates tumor progression." (PMID 31109060, 2019). "Dendritic cells from the circulation of older individuals may also have the potential to guide pro-on within adipose tissue due to increased intracellular IL-6 and TNF-α and increased expression of co-stimulatory and activation markers, as is observed in the context of obesity." (PMID 29479350, 2018). "Interestingly, exercise to reduce obesity associated risk, coupled with dietary controls was sufficient to control the inflammatory response of DIO mice to P. gingivalis challenge, and is accompanied by reduction in circulating TNF-α and FFA." (PMID 29621153, 2018). "Additionally, once obesity develops, insulin resistance and metabolic inflammation due to the dysfunction of adipocytokine secretion, which includes increased tumor necrosis factor-α and resistin as well as a decreased adiponectin, are triggered and result in metabolic dysfunction." (PMID 30537972, 2018). "In obesity, TNF-α, Il-1β, and IL-6 may induce the hepatic release of C-reactive protein (CRP)." (PMID 29189992, 2018). "Furthermore, it was later shown that deletion of TNF-α or its receptor protects mice against diet-induced obesity and insulin resistance, whereas TNF-α blockade by treatment with its monoclonal antibody infliximab improved glucose homeostasis in patients with rheumatic disease." (PMID 30116154, 2018). "Furthermore, TNF-α and IL-6, obesity-related inflammatory cytokines, were decreased." (PMID 30258363, 2018). "Importantly, adequate evidence has shown that TNF-α plays a critical role in obesity." (PMID 29444083, 2018). "Thus, it is likely that increased DRG TNF-α production in obesity may contribute to the maintenance of FM-like pain behaviors." (PMID 29444083, 2018). "However, in recent years, accumulating evidence has demonstrated that TNF-α is increased during obesity and may serve as a pro-cancer cytokine that is involved in carcinogenesis and cancer progression." (PMID 29755407, 2018).
Obesity (continued). "TSH levels have previously been implicated in the development of insulin resistance (IR) and diabetes while TNF-α has been shown to decrease appetite, therefore, lower levels of TNF-α may exasperate obesity related comorbidities by lending to increased positive energy imbalance." (PMID 30473679, 2018). "TNFSF14/HVEM (herpesvirus entry mediator) are involved in obesity-induced inflammation by recruiting and enhancing macrophage lineage in adipose tissue, thus subsequently responsible for the release of several pro-inflammatory cytokines including TNFα, IL6 and MCP-145." (PMID 30242179, 2018). "Il15 ablation in mice has been reported to result in a significant increased weight gain independent of appetite; notably, the mice do not display obesity-associated inflammation, characterized as an increase of serum IL-6 and tumor necrosis factor-α concentrations." (PMID 30382157, 2018). "Similarly, insulin resistance, adipocyte hypertrophy and obesity result from perturbations in the regulation of the inflammatory cytokines interleukin 6 (IL-6) and tumor necrosis factor α (TNF-α) in mice with increased PGRN through Pgrn over-expression or administration of recombinant PGRN." (PMID 30509290, 2018). "Overconsumption of calories disrupts the pattern by causing persistently elevated TNFα, which over time causes functional impairment of hypothalamic POMC neurons, thereby generating an additional pathogenic drive towards impaired energy homeostasis and obesity." (PMID 28489068, 2017). "During the development of obesity, adipose tissue is infiltrated by an increasing number of macrophages, which are considered to be a major source of inflammatory mediators, such as tumor necrosis factor-α (TNF-α) and nitric oxide, that negatively affect adipocyte function." (PMID 28659738, 2017). "Altered expression of immune system molecules such as interleukins IL-1, IL-6, IL-18, tumor necrosis factor alpha (TNF-α), serum amyloid A (SAA), and plasminogen activator inhibitor-1 (PAI-1), among others, has been associated with the development of chronic inflammation in obesity." (PMID 28319103, 2017). "Furthermore, TNF-α knockout mice are protected against obesity-induced insulin resistance." (PMID 28720906, 2017). "Interestingly, our group and others have shown that TNF-α is also a substrate for ADAM19 and therefore it is possible that ADAM19 may have an underlying role in the pathogenesis of obesity and T2D." (PMID 28265178, 2017). "In addition, when used at 10 mg/kg, melatonin was proved to markedly improve non-alcoholic liver steatosis in mice with obesity induced by high fat diet, presenting the decreased TNF-α, IL-1β, IL-6, and phosphorylation of p38 and JNK1/2, indicating the MAPK-JNK/p38 signaling pathway was involved." (PMID 28387721, 2017). "As plasma and adipose tissue concentrations of proinflammatory cytokines, like IFN-γ and TNF-α, are elevated in obesity, the leptin-mediated decrease of IFN-γ secretion by NK cells may be a local effect occurring in regions of NK cell defense against tumor cells." (PMID 28357137, 2017). "The accumulation of excess lipids in fatty tissue in obesity leads to adipocyte dysfunction, hypoxia, oxidative stress, and chronic inflammation, accompanied by the release of proinflammatory and diabetogenic cytokines, such as tumor necrosis factor alpha (TNF-α), interleukin 6 (IL6), etc.." (PMID 29321950, 2017). "In the presence of risk factors, such as obesity, aging-related microvascular rarefaction is correlated to adipose tissue activation of the ADAM 17/TACE gene, encoding for a metalloproteinase that is able to cleave out the active TNF-α polypeptide from pro-TNF-α." (PMID 29118467, 2017). "Likewise diabetes, obesity generally constitutes a chronic inflammatory state, particularly elevated leukocyte counts, activity of granulocyte phagocytosis and oxidative burst, and increased levels of TNF-α and IL-6." (PMID 29104871, 2017).